IFNG (interferon gamma)
Diseases named in the same sentence as IFNG in open-access papers (continued):
Sharing a sentence is not in itself a finding about the gene and the disease.
tumor (continued). "This was marked by an increased T cell tumor infiltration and a dose-dependent increase in serum IFNγ." (PMID 34688033, 2021). "In summary, the inflammatory cytokine in the tumor microenvironment TNFα can synergistically augment the effect of T cells-derived cytokine, IFNγ, on the expression of immunosuppressive ligand, PD-L1 in HepG2 cells favoring tumor immune escape phenomenon." (PMID 34445462, 2021). "The JAK-STAT gene set was enriched in up-regulated DEGs as a downstream pathway of interferon-gamma signaling, which is an essential responsive cytokine in cytotoxic T cells mediated killing of tumor cells." (PMID 33708243, 2021). "The present study will contribute to enhancing our understanding of interferon gamma response genes, its role in regulating cellular pathways, affecting immune cell-infiltration and immune checkpoint gene expression in tumor microenvironment." (PMID 33839701, 2021). "When CD8 T cells were depleted from melanoma, TILs and the remaining T cells (median 89% CD4 T cell composition assessed by flow cytometry) were assayed for tumor reactivity; about 20% showed tumor reactivity as assessed by IFNγ production." (PMID 34140957, 2021). "Although IFNγ has been regarded as an anti-tumor cytokine, recent studies have demonstrated that IFNγ has a ‘double-edge’ effect in tumor progression." (PMID 33849634, 2021). "An additional approach with the HIS-mouse model is the ability to genetically manipulate the HSC prior to “humanization,” and thus track a tumor-specific T cell receptor or test the role of distinct genes in a response (e.g. knock-out IFNγ)." (PMID 33854497, 2021). "They develop in the bone marrow and traffic into solid tumors, where they accumulate mediated by factors such as GM-CSF, M-CSF, G-CSF, VEGF, IFNγ, IL-6, and IL-4, which are secreted by the tumor cells themselves or other cells of the TME." (PMID 34795675, 2021). "Taken together, our in vitro and in vivo data demonstrates that SHP2 blockade enhances IFNγ signaling in tumors and triggers anti-tumor immunity via cytotoxic T cell recruitment and activation." (PMID 33446805, 2021). "Treatment with MCLA-145 increased IFNγ production in all tumor samples relative to control antibody and, to a lesser extent, comparator antibodies." (PMID 34290245, 2021). "In this preclinical study, co-culture of CAR T cells with B7H6+ tumor cell lines produced enhanced interferon-gamma (IFN-γ) secretion and induced significant cytotoxicity." (PMID 35011583, 2021). "B cells have been shown to promote anti-tumour immunity through the release of inflammatory cytokines, such as IFNγ and IL-12, and directly attack tumour cells via production of granzyme B and TRAIL in hepatocellular carcinoma." (PMID 34885021, 2021). "Interferon-gamma (IFN-γ) is an important cytokine produced by activated T cells, NK and NK T cells in the tumor microenvironment, where it orchestrates innate and adaptive antitumor immune responses." (PMID 33779796, 2021). "Lastly, the secretion of cytokines, including IFNγ and IL-12, by B cells promotes further activation of anti-tumor CD8+ T cells and NK cells." (PMID 34458583, 2021). "Our ORA bioinformatic analysis provides putative tumor promoting pathways to investigate that would be acquired during chronic IL-1 exposure, such as insulin and interferon gamma signaling, glucose homeostasis and metabolism and cell adhesion." (PMID 34988553, 2021). "Metabolic competition by tumor cells restricts T cells and dampen their interferon gamma (IFNγ) production and other functions, thus facilitating tumor progression." (PMID 34888248, 2021). "Globally, this assay can provide insight on how CAR T cells are acting within a solid tumor setting and how the heterogeneity effector genes such as GZMB and IFNγ of the CAR T cell population affects the reduction in tumor size." (PMID 34155235, 2021).
tumor (continued). "In another study, loss of Elf5-FBXW7 in triple negative breast cancer cells was shown to increase IFNγ signaling, leading to enhanced PD-L1 expression on tumor cells and accumulation of immunosuppressive neutrophils in the TME." (PMID 33801234, 2021). "Recently, Zaidi reported that IFNG has dual roles as a tumor suppressor and protumor factor in cancer." (PMID 34257587, 2021). "IFNγ plays a key role in modulating the immune response toward these effector cells in the tumor microenvironment." (PMID 35003017, 2021). "In fact, the upregulation of CD73 and IFNγ observed in the healthy matrix opposes to a significant reduction of both genes in the tumor condition." (PMID 34070750, 2021). "In response to IFNγ (interferon gamma), MDSCs release the tumor-promoting and immunosuppressive molecule nitric oxide (NO), whereas macrophages largely express antitumor properties." (PMID 34199169, 2021). "Another study found that a distinct subset of DCs (CD11b+CD103-) predominated in PDA and induced tumor-promoting FOXP3-IL-10+IL-17+IFNγ+ regulatory CD4+ T cells through the secretion of IL-23 and TGF-β." (PMID 34290984, 2021). "Both SHP099 and TNO155 upregulated CXCL10 secretion upon rhIFNγ treatment; in addition, SHP2 blockade lowered the dose of rhIFNγ required to affect OVCAR-8 cell viability, indicating that SHP2 inhibition sensitized tumor spheroids to IFNγ." (PMID 33446805, 2021). "CD73 and A2AR reduced viability, cytotoxicity and IFNγ expression in tumor-infiltrating NK cells and CD8+ T cells." (PMID 34359884, 2021). "In the tumor microenvironment, PD-1 expression is sustained highly on exhausted T cells, followed by the diminished production of effector factors, including interferon-gamma (IFN-γ), interleukin-2 (IL-2), and tumor necrosis factor-alpha (TNF-α)." (PMID 34819055, 2021). "Tumor-infiltrating lymphocytes present in the tumor microenvironment are a major source of IFNγ to increase tumor cell PD-L1 expression." (PMID 34240739, 2021). "The efficacy of immune checkpoint blockade depends on the infiltration and activation of anti-tumor T cells, which subsequently induce significant elevation of IFNγ in the TME." (PMID 33849634, 2021). "This nanoparticle approach acts to potentiate immunotherapy by recruiting tumor-infiltrating T lymphocytes for interferon gamma (IFNγ) secretion." (PMID 34572802, 2021). "Overall, our observations showed that IL-17 and IFNγ jointly but not individually transformed normal BMSCs into TA-MSCs, and the IL-17 and IFNγ transformed TA-MSCs can recruit myelocytes into the tumor microenvironment to promote tumor growth." (PMID 33889575, 2021). "Tumor cells with activated IFNγ pathways can respond to cytokine secretion by immune cells located into the TME and become visible to T cells." (PMID 33406696, 2021). "With increased tumor PD-L1, expression of activation and cytotoxicity marker genes, including IFNG, TNFSF9, TNFSF14, CSF2, and IL2, were downregulated in both Tnull and TCR-TMART-1, consistent with results of cytokine secretion assays." (PMID 33754038, 2021). "The implantation of β3-integrin-depleted tumor cells led to immune “hot” tumors, with decreased PD-L1 expression, increased local IFNγ production and CD8+ T cell infiltration, diminishing tumor growth." (PMID 34065396, 2021). "The reprogrammed GBM-infiltrating Treg cells express genes associated with a Th1 response signature, produce IFNγ, and acquire cytotoxic activity against GBM tumor cells while losing their suppressive function." (PMID 33976133, 2021). "Reduced frequency was associated with dysfunctional activity and characterized by lower levels of IFNγ and reduced cytotoxic activity, with less granzyme B and perforin production and a reduced capacity to kill tumor cells." (PMID 33679803, 2021). "IFNγ is a cytokine that plays an important role in tissue homeostasis, immune and inflammatory responses, and tumor immune monitoring." (PMID 35111153, 2021).
tumor (continued). "Anti-tumor properties of M1-like TAMs include tumor-cell killing abilities, which are mediated by the production of NO, ROS, and IFNγ." (PMID 34202449, 2021). "Using several mouse tumor models, IFNγ was shown to be essential for CTL-driven development of immune-resistant cancer cell clones through increased tumor cell genetic instability." (PMID 33801234, 2021). "Induction of anti-tumor NK and T cell responses lead to the secretions of the type II interferon-gamma (IFN-γ) that will further shapes the immunogenicity and the immunosuppressive microenvironment of the tumor with the IFN I." (PMID 34249754, 2021). "Th1 polarized CD4+ T-cells orchestrate and maintain anti-tumor immune response by directly secreting effector cytokine such as IFNγ and TNFα and also by activating and supporting cytotoxic CD8+ T-cells." (PMID 34012510, 2021). "Several lines of evidence have confirmed that ferroptosis enhanced the tumor suppression mediating by interferon-gamma (INF-γ) secreted by CD8+ T cells in response to immune checkpoint blockade." (PMID 35154262, 2021). "Activated and proliferating lymphocytes play a role in cytotoxic cell death and inhibit tumor cell proliferation and migration by secreting cytokines such as interferon gamma (IFN-γ) and tumor necrosis factor alpha (TNF-α)." (PMID 34830555, 2021). "Tumor tissue showed a high amount of IFNγ, IL-6, and TNFα, which is consistent with a phenotype of TIL activation." (PMID 33986267, 2021). "Compared with WT mice, the faster tumor growth and bigger tumor size/weight were determined in control IFNγ-/- mice." (PMID 33456564, 2021). "Tumor cell encounter in the bioprinted 3D tumor model induced release of lower levels of the cytokine, interferon gamma (IFNG), from L1CAM-CAR T cells than encounter in 2D cocultures (SS-BB/ζ: p=0.07; LS-BB/ζ: p=0.06)." (PMID 34267756, 2021). "In contrast, co-culturing MyLa cells with MF tumor-derived fibroblasts significantly suppresses the expression of IFNG (p < 0.0002) and TBX21 (p < 0.0004) in MyLa cells." (PMID 33941102, 2021). "Purification also resulted in the improved recognition of endogenously processed and presented peptide in the NY-ESO-1-positive tumor cell lines Saos-2 and U226 when assessed by IFNγ release." (PMID 34514030, 2021). "DFT2 cells express comparable levels of STAT3 to DFT1, which do not change upon treatment with IFNγ in either cell line, and lower levels of Interleukin 1 Receptor, Type 1 (IL1R1), which is upregulated by both tumours in response to IFNγ." (PMID 34780568, 2021). "Although tumor-infiltrating immune cells and tumor-specific IFNγ-expressing splenocytes in vitro were increased after mVG161 treatment in CT26 tumor-bearing mice, the differences compared to VG160 were not significant." (PMID 34578321, 2021). "Tumor PD-L1 expression originates from both intrinsic and external sources, driven by oncogenic activation and induced by IFNγ production from T cells." (PMID 34496872, 2021). "In contrast, IFNβ and IFNγ in the cGAMP-treated LLC tumours was similar between STINGΔMC mice and WT mice." (PMID 34285232, 2021). "CD8+ cell secret cytotoxic molecules and cytokines, including perforin, granzyme, interferon-gamma, tumor necrosis factor-alpha and so on, which elicit anti-tumor effects." (PMID 34795362, 2021). "Analysis of specific genes involved in CD4+ differentiation and function revealed differential methylation status of TBX21, GATA3, RORC, FOXP3, IL10 and IFNG in tumor CD4+ T-cells." (PMID 34012510, 2021). "The expression levels of IFNG were significantly higher in the primary tumor than in the normal cervix samples." (PMID 33390854, 2021). "The expression of both PD-L1 mRNA and protein in tumor cells can be upregulated by T cell-secreted IFNγ, which provides a mechanism for cancer to suppress T cell immune responses via ligating T cell surface PD-1." (PMID 33849634, 2021).
tumor (continued). "CAR T cells can mediate tumor-specific cytotoxicity, for example by releasing IFNG, which is necessary for complete tumor eradication, or by inducing the Fas/FasL axis." (PMID 34267756, 2021). "The adoptive transfer of PD-1−/− DCs increases CD8+T-cells infiltrations along with IFNγ, IL-2, perforin and GZMB secretions in the TME and thereby causing rapid tumor control." (PMID 34571899, 2021). "Here, when tumor cells are attacked by the immune system, interferon gamma is overexpressed through the active anti-tumor immune response." (PMID 34283076, 2021). "In particular, lymphocytes lose their ability to produce interferon-gamma (INF-γ)–a cytokine with an important significance in the tumor microenvironment influencing the PD-L1 expression on tumor cells." (PMID 34502043, 2021). "Expression of the M1 marker IFNG was relatively low in macrophages from the tumor as well as the normal lung." (PMID 33918618, 2021). "Mechanistically, we investigated if the inhibition of tumor growth by D-Nap-GFFY-T317 is completed through activation of IFNγ production, particularly by macrophages and DCs." (PMID 33456564, 2021). "In MCA205-Luc2 tumors, depletion of NK cells with antibodies or CXCR3 blockade has been shown to promote tumor growth due to reduced IFNγ and upregulation of IL-17A and VEGF-A, modifying the TME and recruitment of suppressive neutrophils of PMN-MDSCs." (PMID 33953710, 2021). "The most prominent pro-inflammatory molecule that has been ascribed to this process is interferon-gamma (IFN-γ), which is secreted by tumor-associated antigen specific T cells in the TME." (PMID 33919570, 2021). "Among all the genes reported in the literature with their potential cause in tumor development, CPEB4, APC, TRIP13, EIF2S3, EIF4A1, IFNg, PIK3CA and CTNNB1 have particularly been identified to be a set of potential candidates for tumor development." (PMID 33237662, 2021). "In a preclinical mouse study, selective deletion of HIF-1α in T cells led to increased tumor growth and decreased T cell tumor infiltration, survival, and effector function, measured by production of TNFα and IFNγ." (PMID 34868044, 2021). "This happens directly by CD8 T cells killing the tumor cells or indirectly by activating NK cells or macrophages after cytokine release such as IFNg." (PMID 33679794, 2021). "In a lipid-rich environment, the lipid sensor PPARγ agonist rosiglitazone, which is already in use in clinics, promotes IFNγ secretion, and thus the in vitro anti-tumor activity of NK cells." (PMID 34696286, 2021). "It has been demonstrated that IFNγ entrapment by galectin-3 in the tumor extracellular matrix prevents the creation of such a chemokine gradient required to attract T cells towards the tumor." (PMID 34572756, 2021). "Interferon gamma (IFN‐γ) cytokine that is secreted by the infiltrating antitumor CTLs into tumor microenvironment, plays a key role in induction of PD‐L1 expression." (PMID 33369247, 2021). "Interferon-gamma (IFN-γ) has a dual role in tumour progression, inhibiting it when at low levels and promoting at high levels." (PMID 33916290, 2021). "Destruction of mouse tumor stroma by human T cell effector molecules such as IFNG is also excluded in these models but is critical for solid tumor eradication." (PMID 33801448, 2021). "This subpopulation of neutrophils is triggered by a combined effect of IFNγ and GM-CSF within the tumor." (PMID 34572138, 2021). "Here, we report that HSD induces natural killer (NK) cell–mediated tumor immunity by inhibiting PD-1 expression while enhancing IFNγ and serum hippurate." (PMID 34516769, 2021). "The literature has indicated that immunotherapy targeting PD-1 and CTLA-4 specifically increases CXCL9 and CXCL10 from tumor-associated macrophages in tumor tissues, whereas CXCL9 and CXCL10 are induced by IFNγ in the tumor microenvironment." (PMID 34680466, 2021).
tumor (continued). "ELISA data showed that both IFNγ and TNFα were released from activated T cells in response to hEx3 treatment in a dose-dependent manner, although cell contact-dependent tumor cell killing is the major MOA of the TDB." (PMID 32666260, 2021). "Non-replicative AAV and replicative HSV have also been used to express IL12 in malignant glioma, resulting in significant inhibition of tumor growth and increased expression of IFNγ with microglial activation and recruitment of T and NK cells." (PMID 33790740, 2021). "NK cells are innate lymphoid cells involved in tumor immunosurveillance by inducing cancer cell lysis either directly (via perforin/granzyme system) or indirectly (via secretion of TNFα and IFNγ)." (PMID 34638439, 2021). "In fact, compared to PBS-treated tumours, cGAMP-treated tumours showed 3.9-fold and 2.2-fold increases of TNFα and IFNγ, respectively." (PMID 34285232, 2021). "Specifically, TGF-β-induced phosphorylation of SMAD2/SMAD3 in NK cells leads to decreased IFNγ production and decreased anti-tumor cytotoxicity with phenotypic downregulation of the activating receptors NKG2D, NKp30, DNAM-1, TRAIL, and CD16." (PMID 33766099, 2021). "Extrinsic induction of PD-L1 in tumors is generally mediated by proinflammatory cytokines derived from tumor-infiltrating lymphocytes (TILs), mainly interferon gamma (IFNγ)." (PMID 34445462, 2021). "Increased interferon gamma (IFNγ) production by NK cells can induce PD-L1 expression on tumor cells and immune cells within the TME, providing a rationale for the possible synergistic potential of combining cetuximab with anti-PD-1 therapy." (PMID 35047999, 2021). "Our study revealed that upon stimulation with rituximab- or obinutuzumab-opsonized tumor cells, memory NK cells display a higher frequency of multifunctional IFNγ+CD107a+ cells with respect to the conventional population." (PMID 34065399, 2021). "On the other hand, the heat-inactivated supernatant with either recombinant IFNγ or recombinant TNFα exhibited partial restoration of tumor cell killing activity." (PMID 32666260, 2021). "We measured the IFNγ, CD8+, cleaved caspase 3, Ki67, and PD‐L1 protein levels by IHC staining to uncover the mechanism underlying tumor growth suppression by FGFR inhibitor and immunotherapy." (PMID 34514747, 2021). "Loss of ANKRD52 caused a remarkable downregulation in the expression of IFNγ and IFNα responsive gene sets after MC38 cells were stimulated with IFNγ, a T cell cytokine essential for tumor immunity." (PMID 34853298, 2021). "Co-culture of MPE-derived lymphocytes with tumor cells or known tumor antigens from lung cancer patients resulted in IFNγ production and CD137 expression, suggesting tumor reactivity." (PMID 33987104, 2021). "Competition between T cells and cancer cells for glucose within the tumor microenvironment restricts the glycolytic capacity and IFNγ production of T cells, allowing for tumor progression." (PMID 34283042, 2021). "Pro-inflammatory, or “anti-tumor”, macrophages contribute to an anti-tumor response by producing pro-inflammatory cues such as IFNγ and IL-12 secretion or by acquiring an antimicrobial and tumoricidal phenotype." (PMID 33953710, 2021). "Cytokines, such as IFNα, IFNγ, IL-2, and GM-CSF, which induce B cells, T cells, NK cells, and macrophages for tumor cell killing, have been successfully used for gastrointestinal cancer treatment." (PMID 33406733, 2021). "In a reciprocal way, the resistance to PD-L1 therapy is also related to the defect of IFNγ signaling pathway in tumor cells." (PMID 34365463, 2021). "Background and purpose: Activation of liver X receptor (LXR) by its ligand T0901317 (T317) enhances interferon-γ (IFNγ) production to inhibit tumor growth." (PMID 33456564, 2021). "First, T cell recruitment towards the tumor requires an IFNγ-induced CXCL9/10 gradient of chemokines." (PMID 34572756, 2021).